RNF5 (ring finger protein 5)
Diseases named in the same sentence as RNF5 in open-access papers (continued):
Sharing a sentence is not in itself a finding about the gene and the disease.
tumor (continued). "Rnf5−/− tumor-infiltrating CD4+ and CD8+ lymphocytes (TILs) also displayed greater effector function, including enhanced IFN-γ, TNF-α, and IL-2 production." (PMID 30940817, 2019). "Here, we demonstrate that Rnf5−/− mice exhibits altered intestinal microbiota flora, which contributes to antitumor immunity, limiting tumor expansion." (PMID 30940817, 2019). "Expression of MHC class II as well as CD80 and CD86 molecules was also higher on tumor-infiltrating macrophages from Rnf5−/− compared with WT mice." (PMID 30940817, 2019). "Chemokine (C–C motif) ligand 5 (CCL5), which is associated with TLR signaling, was also upregulated in serum from tumor-bearing Rnf5−/− compared with WT mice." (PMID 30940817, 2019). "To do so, we examined tumor growth in the bone marrow (BM) chimeric mice created by injection of either WT or Rnf5−/− bone marrow cells into lethally irradiated WT or Rnf5−/− recipients." (PMID 30940817, 2019). "Correspondingly, tumor-bearing Rnf5−/− mice exhibited better survival, compared with the WT genotype." (PMID 30940817, 2019). "Strikingly, ABX treatment largely prevented the inhibition of tumor growth inhibition seen in Rnf5−/− mice, suggesting that the gut microbiota play a key role in the control of tumor growth in the Rnf5−/− mice." (PMID 30940817, 2019). "Of equal importance, we observed that both DCs and pDCs were significantly more abundant in Peyer’s patches (PP) from tumor-bearing Rnf5−/− mice than in naive animals." (PMID 30940817, 2019). "Altogether, these data indicate a clear shift to a proinflammatory tumor microenvironment in Rnf5−/− mice." (PMID 30940817, 2019). "Since PEL constitutively activates the phosphatidylinositide 3-kinase (PI3K)-Akt and extracellular regulated kinase (ERK)-MAPK pathways, we investigated the role of RNF5 in lytic replication and the tumor-suppressive effect of RNF5 inhibition in PEL using different approaches." (PMID 36656913, 2023). "In particular, we hypothesize that the activity of RNF5 is related to different factors including oncogenic background, metabolic phenotype, epigenetic features and tumor microenvironment." (PMID 35406574, 2022). "RNF5 was expressed with variable intensity by all the tumor cell lines tested." (PMID 35406574, 2022). "Depending on tumor model tested, RNF5 exerts pro- or anti-tumor activity." (PMID 35406574, 2022). "Overall, altered IEC immunogenicity and expression of antimicrobial peptides are expected to impact DC cell activation and microbiota composition, which together are expected to define the antitumor immunity and tumor growth inhibition, as seen in the Rnf5−/− mice." (PMID 30940817, 2019). "Likewise, tumor-bearing Rnf5−/− mice had enhanced frequency of CCR7+ DCs isolated from GALT and of CCR7+ mDCs isolated from MLN, compared with those isolated from the WT tumor-bearing mice." (PMID 30940817, 2019). "We thus investigated the potential effect of RNF5 on immune checkpoint control and tumor growth." (PMID 30940817, 2019). "Enhanced cytokine and chemokine expression were observed in IECs from tumor-bearing Rnf5−/− mice." (PMID 30940817, 2019). "Hence, RNF5 can potentially impact immune-checkpoint control and tumor growth." (PMID 35992663, 2022). "Our ability to identify a select subset of bacterial strains that are enriched in the Rnf5−/− mice, which can elicit antitumor immunity and tumor growth inhibition when administered to GF WT mice, establish the importance of specific commensals in tumor growth control." (PMID 30940817, 2019). "Notably, DCs isolated from the gut-associated lymphoid tissue (GALT) including PP, mesenteric lymph node (MLN), and tumor-draining lymph node (TdLN) of tumor-bearing Rnf5−/− mice induced more T cell cytokine production compared with DCs isolated from WT tumor-bearing mice." (PMID 30940817, 2019).
tumor (continued). "Another group found that the inhibition of Ring finger protein 5 (RNF5), an ER-localized E3 ligase, decreases PEL xenograft tumor growth and downregulates both viral and cell cycle gene expression." (PMID 39518131, 2024). "Therefore, our results indicate that RNF5 inhibition could switch EphA2 from tumor-promoting to tumor-suppressive functions by promoting its stability and cell-surface distribution, inducing the unbalance of EphA2 phosphorylation and then decreasing ERK-MAPK activation." (PMID 37816703, 2023). "We found that RNF5 KO decreased genomic viral DNA loads in BCBL1-derived subcutaneous tumors, indicating that RNF5 KO decreased spontaneous lytic replication and genomic viral DNA loads during BCBL1-derived tumor growth." (PMID 36656913, 2023). "Additionally, circDHX8 can competitively bind to RNF5, inhibiting the interaction between ATG2B and RNF5 to maintain the stability of ATG2B protein, thus promoting autophagy and tumor development in GC." (PMID 39901896, 2025). "We next created a cocktail of 12 bacterial strains that displayed a significant negative correlation with tumor size and were overrepresented in Rnf5−/− mice compared with WT counterparts." (PMID 30940817, 2019). "Accordingly, RNF5 depletion using shRNA approaches or inhibition using the INH2 compound increased cell surface EphA2 levels, decreased ERK and AKT phosphorylation, and altered the balance of EphA2 phosphorylation at S897 and Y772, resulting in a tumor-suppressor function." (PMID 39596256, 2024). "To further measure the effect of RNF5 inhibition on PEL tumorigenesis, we subcutaneously injected stable control BCBL1 cells or BCBL1 cells with RNF5 knockdown by shRNA or RNF5 KO using CRISPR-Cas9 into NOS/SCID mice and measured xenograft tumor growth in mice derived from these PEL cells." (PMID 36656913, 2023). "Prophylactic transfer of Rnf5−/− microbiota was sufficient to delay tumor growth, as well as to enhance infiltration of tumor-specific CD45+, CD4+, CD8+ T cells and increase cytokine production, supporting a role for the Rnf5−/− microbiota in mediating antitumor effects." (PMID 30940817, 2019). "Therefore, targeting PTEN destabilizers such as RNF5 may provide a unique approach to restore PTEN function in both tumor cells and tumor stromal fibroblasts." (PMID 30456390, 2018). "Analysis of tumor-draining and non-draining lymph nodes revealed that OT-I CD8+ T cells were more abundant in the draining lymph nodes of Rnf5−/− compared with WT mice." (PMID 30940817, 2019).
infection (15 papers, 2012 to 2025). The state of being infected such as from the introduction of a foreign agent such as serum, vaccine, antigenic substance or organism. "Our results identify RNF5-mediated E protein degradation as a potential therapeutic strategy to treat infections caused by SARS-CoV-2 and related viruses." (PMID 36737599, 2023). "The results showed that following RNF5 knockout, HBeAg levels progressively increased at 3, 5, and 7 days post-infection, while HBV DNA and HBc were significantly upregulated, with a more pronounced increase compared to WT cells." (PMID 40236486, 2025). "The use of Analog-1, a pharmacological activator of RNF5, was shown to mitigate disease progression in a mouse infection model." (PMID 39823440, 2025). "For example, the newcastle disease virus V protein recruits E3 ubiquitin ligase RNF5 for polyubiquitination and degrades the mitochondrial antiviral signal protein, thereby inhibiting interferon production and facilitating self-infection." (PMID 36831257, 2023). "The RNF5 activator Analog-1 has been shown to significantly inhibit SARS-CoV-2 replication in infection models, making it a potential candidate for treating infections caused by related viruses." (PMID 38250078, 2023). "Given the fundamental role of STING and MAVS in triggering type I interferon signaling following infection, numerous viruses have developed ingenious strategies to counteract antiviral immunity through the modulation of RNF5." (PMID 38250078, 2023). "The subsequent analysis of the clinical scores and tear virus titers showed that RNF5 silencing effectively limited viral replication at the site of infection and alleviated HSK symptoms." (PMID 35992663, 2022). "Studies have shown that RING finger 5 (RNF5) targets STING for K48-linked ubiquitination and proteasome-dependent degradation during infection by the RNA virus Sendai virus, thereby inhibiting the activation of downstream signaling pathways." (PMID 35992663, 2022). "Infection with group A Streptococcus was lower in RNF5-/- mice because autophagosome formation increased and mediated the clearance of bacteria by RNF5-/- macrophages." (PMID 35456009, 2022). "In this study, we found that the expression of RNF5 was elevated in corneal tissues and corneal epithelial cells after infection with HSV-1." (PMID 35992663, 2022). "Wild-type and RNF5 KD Vero cells were infected with SARS-CoV-2 with a multiplicity of infection (MOI) of 0.05, and a plaque assay was subsequently performed." (PMID 35100873, 2022). "The results showed that the expression level of RNF5 was significantly increased compared with the baseline level (on the day of infection)." (PMID 35992663, 2022). "The results showed that the expression of RNF5 in the cells was significantly increased after infection with HSV-1." (PMID 35992663, 2022). "The tear analysis showed that the virus titers of the tears were lower in the RNF5-siRNA group than in the siRNA-control group at 1, 3, and 5 days after the infection." (PMID 35992663, 2022). "We detected a marked increase in RNF5 expression on the third day after the infection when the epithelitis was most obvious." (PMID 35992663, 2022). "Infection experiments at the indicated times showed that transient overexpression of RNF5 in HEK293 cells facilitated SZ19 viral replication, whereas viral titers were markedly reduced in RNF5-deficient cells." (PMID 33577621, 2021). "Using RNF5 mutant mice we demonstrate the implications of this regulation for host defense mechanisms that limit intracellular infection by bacterial pathogens." (PMID 23093945, 2012). "The higher basal levels of autophagy in these mice allow more efficient clearance of invading bacteria, reducing both the load and physiological consequences of infection, as reflected in the improved survival of RNF5−/− mice following infectious challenge." (PMID 23093945, 2012).
infection (continued). "Lastly, RNF5 contributes to the cellular response to infection by controlling the stability of the mitochondrial proteins MITA and MAVS, which are involved in antiviral innate immune signaling." (PMID 23093945, 2012). "The bacterial loads in mouse organs during the early stages of infection were higher in RNF5+/+ mice compared to RNF5−/− mice." (PMID 23093945, 2012). "Importantly, the RNF5 pharmacological activator Analog-1 alleviates disease development in a mouse infection model." (PMID 39823440, 2025). "The balance between RNF5-mediated K48-linked ubiquitination and RNF26-mediated K11-linked polyubiquitination is crucial for efficient type I IFN and proinflammatory cytokine induction following infection." (PMID 38250078, 2023). "Furthermore, RNF5 expression was found to increase in corneal tissues and corneal epithelial cells during infection with HSV-1, which, like PRV, is a neurotropic herpesvirus." (PMID 38250078, 2023). "Importantly, we found that the RNF5 activator Analog-1 effectively inhibits SARS-CoV-2 replication in infection models using cultured cells and mice, making it a candidate agent against infections caused by SARS-CoV-2 and related viruses." (PMID 36737599, 2023). "Importantly, RNF5-induced degradation of E inhibits SARS-CoV-2 replication and the RNF5 pharmacological activator Analog-1 alleviates disease development in a mouse infection model." (PMID 36737599, 2023). "Therefore, we next explored the role and specific molecular mechanisms of RNF5 in infection with the double-stranded DNA virus HSV-1." (PMID 35992663, 2022). "Collectively, these results indicate that during HCEC infection with HSV-1, RNF5 could aggravate the infection by inhibiting the STING/IRF3 signaling pathway and reducing the expression of IFN-β." (PMID 35992663, 2022). "Moreover, the intensity of the fluorescence staining was significantly enhanced on the third day after the infection, which further confirmed the increased expression of RNF5 in the corneal tissue in HSK." (PMID 35992663, 2022). "Therefore, we aimed to determine whether the host-derived E3 ubiquitin ligase RNF5 is involved in the infection process of HSV-1 and characterize the role of RNF5 in the occurrence and development of HSK." (PMID 35992663, 2022). "Our study demonstrated that iRhom2 antagonizes RNF5 and MARCH5 at different stages of infection respectively, representing one of the spatiotemporal mechanisms of VISA regulation." (PMID 29155878, 2017). "Interestingly, RNF5 has recently been found to play a novel role in regulating SARS-CoV-2 viral replication and infection." (PMID 38250078, 2023). "Furthermore, the RNF5 agonist Analog-1 effectively inhibits SARS-CoV-2 infection in both cells and a mouse infection models." (PMID 36737599, 2023). "Moreover, during infection with herpes simplex virus type 1 (HSV-1), RNF5 expression is upregulated in corneal tissues and corneal epithelial cells." (PMID 38250078, 2023). "Notably, the RNF5 activator Analog-1 was found to effectively suppress FMDV replication in infection models utilizing cultured cells and mice, positioning it as a promising agent against FMDV-induced infections." (PMID 39823440, 2025). "Moreover, infection was increased in SHARPIN KO cells and decreased in RNF5 KO cells." (PMID 38140653, 2023). "Furthermore, the absence of RNF5 significantly enhanced viral mRNA levels at 12 and 18 hours post-infection (hpi), regardless of whether the viral RNA was located intracellularly or extracellularly." (PMID 39823440, 2025). "Following transfection of IBRS-2 cells with negative control (NC) siRNA, siRNA-1, or siRNA-2 of RNF5 or RNF81, and subsequent infection with FMDV, the viral RNA levels, protein expression, and titers were compared." (PMID 39823440, 2025). "Unlike RNF5 and GP78, we noticed that knockdown of MARCH5 mainly inhibited virus-triggered down-regulation of VISA at the late phase of infection (10 h)." (PMID 29155878, 2017).
infection (continued). "Given the important role of STING in activating the type I IFN signaling pathway after infection, it is not surprising that many DNA viruses have evolved mechanisms to counteract STING’s function and facilitate their activities within host cells by manipulating RNF5." (PMID 38250078, 2023).
cancer (12 papers, 2018 to 2025). A tumor composed of atypical neoplastic, often pleomorphic cells that invade other tissues. "A further assessment of RNF5-dependent regulation of T cells indicated that RNF5 deficiency inhibits functional T cell exhaustion upon chronic antigen exposure, which often occurs in cancer." (PMID 35406574, 2022). "A specific and selective RNF5 inhibitor, INH2, has been developed and provides a promising approach for further investigation of RNF5 function and therapeutic potential in cancers and other diseases." (PMID 36656913, 2023). "RNF5 is an E3 ubiquitin ligase involved in various physiological processes such as protein localization and cancer progression." (PMID 38250078, 2023). "RNF5 has been reported in ER stress, autophagy, and cancers." (PMID 33684176, 2021). "However, whether RNF5 acts as a therapeutic target for viral infection or cancer chemotherapy remains unclear." (PMID 36656913, 2023). "However, in cancer, the role of RNF5 is still controversial." (PMID 35406574, 2022). "RNF5 (also known as RMA1) is an E3 ubiquitin ligase involved in various physiological processes, including protein localization and cancer progression." (PMID 40936702, 2025). "Based on the Cancer Cell Line Encyclopedia (CCLE) and TCGA database, mRNA expression level of RNF5 is abundant in AML compared to other cancer types, and there is a positive correlation between high RNF5 expression and poor survival." (PMID 35008940, 2022). "Higher levels of RNF5 protein were confirmed in AML and CML cell lines compared with other cancer lines." (PMID 34518534, 2021). "Furthermore, protein expression levels of RNF5 in AML cells and peripheral blood mononuclear cells (PBMCs) from independent cohorts of AML patients are higher than other cancer types and control samples." (PMID 35008940, 2022). "Furthermore, RNF5 was able to degrade phosphoglycerate dehydrogenase (PHGDH), the first enzyme of the serine synthesis pathway, which is significantly upregulated in many cancers." (PMID 35406574, 2022).
Bacterial Infection (4 papers, 2012 to 2023). "The implications of this newly discovered layer in the control of autophagy are reflected in the decreased susceptibility of RNF5-deficient mice to bacterial infection with GAS." (PMID 23093945, 2012). "Given the multiple effects of RNF5 on ER stress, innate immunity, and bacterial infection, processes that are each influenced by autophagy, we have examined the possibility that RNF5 may play a role in the control of autophagy." (PMID 23093945, 2012). "RNF5 controls the membrane fraction of ATG4B and limits LC3 (ATG8) processing, aberrant of which may limit basal levels of autophagy and influence susceptibility to bacterial infection." (PMID 23527081, 2013).
degenerative diseases (4 papers, 2008 to 2022). "Meanwhile, the top hyper-methylated DMR was located near the promoter region of both AGPAT1 and RNF5, which have been reported as genes of interest in studies focusing on neurodegenerative diseases such as AD, PD and related dementias." (PMID 36418427, 2022). "Both RNF5 and 1-acylglycerol-3-phosphate O-acyltransferase 1 (AGPAT1) have been implicated in neurodegenerative diseases." (PMID 33981329, 2021). "The increase in RNF5 expression seen in these degenerative diseases could be a consequence of ER overload and/or ERAD dysfunction." (PMID 26183966, 2015). "The increase in RNF5 expression seen in these degenerative diseases could be a consequence of ER overload, ERAD dysfunction, or part of the mechanism engaged in the development of these disorders." (PMID 18270596, 2008).
muscular disorder (3 papers, 2008 to 2023). "RNF5 is also linked to ER stress alone or with JAMP to play a role in ER-associated degradation of misfolded proteins, and RNF5-transgenic mice develop an ER stress-associated muscular disorder." (PMID 37816703, 2023). "The present study establishes a link between RNF5 and specific muscular disorders associated with ER stress." (PMID 18270596, 2008). "Our findings establishes the importance of RNF5 in muscle physiology and in ER stress associated muscular disorders while pointing to the possible use of RNF5 transgenic mouse as a unique model to study the role of ER function in the pathogenesis of degenerative muscle diseases." (PMID 18270596, 2008). "While supporting a role for RNF5 Tg mice as model for s-IBM, our study also establishes the importance of RNF5 in muscle physiology and its deregulation in ER stress associated muscular disorders." (PMID 18270596, 2008).
myopathies (3 papers, 2008 to 2021). "RNF5 is an important player in muscle physiology and ER stress dysregulation, and it is found in cytoplasmic aggregates of an acquired myopathy common in older people, including body myositis (IBM), along with tau and amyloid-β." (PMID 33981329, 2021).
infectious disease (1 paper, 2012). A disorder directly resulting from the presence and activity of a microbial, viral, or parasitic agent in humans. "Taken together, our data show that the negative regulation of autophagy by RNF5 influences the outcome of GAS infection, and demonstrate for the first time a protective role for autophagy in an in vivo model of this important human infectious disease." (PMID 23093945, 2012).